MMP2 (matrix metallopeptidase 2)
Diseases named in the same sentence as MMP2 in open-access papers (continued):
Sharing a sentence is not in itself a finding about the gene and the disease.
tumor (continued). "Here, we observed that CAFs grown in 3D cultures upregulated a variety of MMPs such as MMP-1, MMP2, MMP3, and MMP9, which are major players in tumor angiogenesis, tissue remodeling, repair, and maintenance." (PMID 39700125, 2024). "In tumour xenografts, the expression of multiple characteristic SASP factors, including GATA4, MMP2/10, ITGA2 and GBP1, significantly increased after PRC2 inhibition, contributing to ECM remodelling and tumour regression." (PMID 39270064, 2024). "The use of such an MMP‐2‐sensitive nanomedicine containing DOX and IND increases the concentration of chemotherapy drugs in tumor tissues and extends the duration of drug presence in tumor tissues." (PMID 39545088, 2024). "MMP2 and MMP9 play an important role in tumor invasion and metastasis by degrading fibrillar collagen after cleavage by collagenase." (PMID 38399294, 2024). "Endogenous MMP inhibitors such as Thrombospondin-1 (TSP-1) regulate MMP-2 and MMP-9 activity reducing tumor growth in pre-clinical tumor models." (PMID 38659022, 2024). "Other than this, the expression of MMP2 and MMP9 in 4T1 tumor tissues was inhibited by garlic peel extracts and was positively correlated with the expression of COX‐2." (PMID 39554336, 2024). "MMP-2 and MMP-9 destroy type IV collagen, which is part of the basement membrane, STM, and ensure the invasion of tumor cells into surrounding tissues." (PMID 39274874, 2024). "Chronic stress activates cAMP/PKA signaling pathway through adrenergic receptor ADRB2, leading to increased expression of VEGF, MMP2 and MMP9 to promote angiogenesis and tumor growth." (PMID 39054537, 2024). "Since ECM remodeling promotes the migration and invasion of tumor cells, the activity of MMP-9 and MMP-2 was employed as molecular biomarkers supporting the invasion and migration assay results." (PMID 39309445, 2024). "Mounting evidence suggests that dysregulation of MMPs, particularly MMP2 and MMP17, plays a pivotal role in tumor invasion, metastasis, and the microenvironment in various cancer types." (PMID 39062041, 2024). "Matrix metalloproteinases, such as MMP-2 and MMP-9, are considered potential putative markers for tumor diagnosis in clinical validation due to their easy detection in body fluids." (PMID 38774755, 2024). "By promoting the synthesis of MMP-2 and activation of the AP-1 transcription factor through the ERK, p38, and JNK signaling pathways, Visfatin enhances tumor cell migration." (PMID 38571500, 2024). "Inhibition of FOXM1 has been shown to reduce the expression of MMP-2 and MMP-9, and suppress the migration and invasion of tumor cells." (PMID 39594778, 2024). "Endothelial degradation primarily through matrix metalloproteinases MMP2, MMP7 and MMP9 is not only required for angiogenesis, but also promotes tumor migration and metastasis." (PMID 38935134, 2024). "Immunohistochemistry was employed to assess the expression levels of COX‐2, CD31, VEGFA, MMP2, and MMP9 in tumor tissues in order to investigate the antioxidant properties of garlic peel extract, specifically its ability to suppress COX‐2 expression." (PMID 39554336, 2024). "Regarding MMPs, a slight decrease was observed in the expression of MMP-9, and the level of TIMP-1 was increased; however, lower levels of MMP-2 and TIMP-2 were detected in tumorous tissues compared to adjacent healthy tissue samples." (PMID 39062015, 2024). "In both animal groups, the expression of MMP-2 and MMP-9 genes was significantly decreased in tumor tissues, while the TIMP-1 and TIMP-2 genes were overexpressed." (PMID 39335164, 2024). "Another mechanism by which ALA inhibits tumor metastasis is by reducing vascular endothelial growth factor (VEGF), MMP-2 and MMP-9 protein expression." (PMID 38541002, 2024). "MMPs such as the gelatinases MMP-2 and MMP-9 have a particular contribution to cancer invasion and metastases, with their overexpression being reported in numerous neoplasms, including CRC." (PMID 38792627, 2024).
tumor (continued). "These targets included the matrix metalloproteinase MMP2, which correlated with stroma derived THBS2 (r = 0.85), as well as stroma and tumour derived TNC (r = 0.76 and 0.64 respectively)." (PMID 38890455, 2024). "The MMPs mainly involved in tumor invasion and present in invadopodia are certainly MMP-9 and MMP-2." (PMID 38540096, 2024). "Owing to NIR‐mediated swelling and MMP‐2‐responsive degradation properties of gelatin, GNP–DOX/ICG can achieve tumor accumulation and deeper penetration of drugs, further improving antitumor efficiency." (PMID 39036340, 2024). "The invasion and metastasis of tumor cells are intricately regulated by the ECM, with MMPs, particularly MMP2 and MMP9, playing a crucial role in facilitating tumor formation and metastasis by degrading matrix proteins." (PMID 39759103, 2024). "M2 subtypes have characteristics that are mostly anti-inflammatory and pro-angiogenic, secreting growth factors (VEGF, PDGF) and matrix metalloproteinases (MMP2, MMP9) promoting tumor growth, metastasis, and invasion." (PMID 38935134, 2024). "MMP-2 and MMP-9 are among the most widely studied biomarkers of the MMPs family, which can degrade the ECM and basement membrane of tumor cells, thereby facilitating cancer cell migration and invasion." (PMID 39769029, 2024). "MMP2, a 72 kDa zinc-dependent protein belonging to the MMPs family, cleaves ECM components and plays a key role in tumor growth and metastasis." (PMID 38584845, 2024). "The treatment effectively inhibited the expression of MMP-2 and MMP-9 in tumor tissue, assessed by immunohistochemical staining, and significantly decreased the tumor volume, indicating that EGCG has strong anti-cancer activity in vivo." (PMID 39335164, 2024). "Several studies have demonstrated a strong correlation between the expression of MMP-1, MMP-2, MMP-7, MMP-9, MMP-10, and MMP-12 enzymes, tumour size, cancer progression, lymphatic dissemination, and bloodstream distant metastasis (table in Section 5)." (PMID 39337393, 2024). "This activation leads to the polarization of macrophages towards the M2 type, increased expression, and secretion of MMP2 and MMP9, thereby reshaping the extracellular matrix and facilitating tumor cell invasion and metastasis." (PMID 39695147, 2024). "MMP-2 (gelatinase A) and MMP-9 (gelatinase B) are related to tumor invasion and metastasis by their special capacity to degrade the type IV collagen found in basement membranes." (PMID 37108185, 2023). "Third, novel strategies inhibit the expressions of MMP-9 and MMP-2 and thus reduce HCC invasion, which can result in lower TNM stage in patients and lower tumor metastasis recurrence rate." (PMID 36918768, 2023). "The Hsp90a/uPA/MMP-2 proteolytic axis releases MMP-2, which activates TRPM7, resulting in ECM degradation and promoting the tumor cells’ invasive potential." (PMID 37189782, 2023). "Activation of these cells produces pro-thrombotic and pro-tumorigenic TF and activates STAT3-mediated IL-6, PAI-1, and MMP-2 production (black upward arrows), and RAS/PI3K/SyK/Ki67/cyclin D1 signaling pathways, leading to tumor growth." (PMID 36751299, 2023). "Correspondingly, the overexpression of matrix metalloproteinases (MMPs), including MMP-2 and MMP-9, was shown as principal mediators of tumor invasion and metastasis where decomposition of the extracellular matrix is critical for tumor progression." (PMID 36910721, 2023). "This suggests that MMP-2-responsive de-PEGylation enhanced the cellular uptake of ELNV and provided the essential conditions for activating the tumor-specific immune response." (PMID 37328484, 2023). "In the presented study, the expression of MMP2, MMP9 and TIMP1 genes was assessed in the blood of NSCLC patients at three time points, before the tumor removal surgery, 100 days after surgery and one year after surgery, and in the tumor tissue." (PMID 37509417, 2023).
tumor (continued). "In subsequent studies, we also found that the exosomes of M2 macrophages enhanced the migration ability of tumor cells and promoted the TMT process by regulating the expression of MMP-2, MMP-9, Vimentin, and E-cadherin." (PMID 37367063, 2023). "In gastric cancer, CAF-mediated signaling induces the expression of MMP-2/9, and TIMP-1/2 increases the tumor invasion by activating the JAK2/STAT3 pathway." (PMID 36980785, 2023). "Next, PCNA and MMP-2 expression was down-regulated following HSPB6 overexpression, suggesting the reduced ability of the tumor for migration and proliferation." (PMID 37861934, 2023). "Research has established that MMP-2 and MMP-9 foster tumor invasion and metastasis through collagen degradation, leading to extracellular matrix disruption and consequent cellular dysfunction." (PMID 37881489, 2023). "Different vital tumor-related genes, such as PTEN, VEGF, MMP2, Oct4, and ADAM9, were defined as miR-20b targets." (PMID 36717861, 2023). "Fibronectin can induce the expression of MMP-2, which is responsible for ECM degradation and tumor invasion." (PMID 38102637, 2023). "Compared with the Mod group, the expression levels of MMP-9, MMP-2, VEGF, bFGF, Bax, and Bcl-2 in tumor tissues were reversed by 67%, 74%, 50%, 63%, 80%, and 51%, respectively, after GFG combined with CTX treatment (p < 0.05)." (PMID 37049720, 2023). "The Tie2+ macrophages play a pivotal role in tumor’ neovascularization by activating the PI3K/Akt/mTOR signaling pathway and result in increased expression of angiogenic factor (VEGF, COX-2, MMP-2/-9) in TEMs." (PMID 37304233, 2023). "The results of transcriptome sequencing after knockdown of SNHG25 in HCT-116 cells showed that the expression of several tumor metastasis-related genes changed significantly (MMP2, VIM and CDH1), among which the expression of MMP2 decreased most." (PMID 37751586, 2023). "Many studies have confirmed that MMP2 and MMP9 are highly expressed in many malignant tumor cells and their stromal components." (PMID 37686118, 2023). "In xenografted animal models of tumor and HeLa cells, CBS downregulated the expressions of nuclear-translocated p65 and molecules downstream of NF-κB (XIAP, Bcl-xL, MMP-2, MMP-9, COX-2, and cyclin D1) by inhibiting the NF-κB signaling pathway." (PMID 37063281, 2023). "On the other hand, the vaccine reached the tumor site, releasing Zn2+ in acidic tumor microenvironment, improving the activity of MMP‐2, promoting ECM collagen degradation, and enhancing tumor invasion and killing of CD8+ T cells." (PMID 37439462, 2023). "Moreover, 22 was shown to inhibit matrix metallopeptidase 2 (MMP2), which is important for metastasis due to the suppression of the immune system, the degradation of the extracellular matrix and the modulation of various pathways that facilitate tumor invasion and progression." (PMID 37298471, 2023). "The new series of sulfa azo 4H-chromene esters (7a–g, 8, and 11a–e) were adapted and assessed for their inhibitory behavior against the HCT-116, MCF-7, and HepG-2 tumor cell lines, targeting EGFR, MMP-2, and Carbonic anhydrase CAII." (PMID 38069037, 2023). "In nasopharyngeal carcinoma, thrombin-induced PAR-1 activation increases the expression of MMP-2 and MMP-9, thus facilitating ECM degradation and destruction of basement membrane by tumor cells." (PMID 37046617, 2023). "MMP2-mediated proteolytic remodeling of the ECM and changes in collagen content provide a mechanism for regulating directional cell motility and tumor invasion in prostate cancer." (PMID 37894275, 2023). "In our study, we found several MMP molecules to be significantly overexpressed in metastatic cell lines compared to primary tumor cells (e.g., MMP1, MMP2, MMP3, MMP9), with a dramatic increase registered for MMP2." (PMID 37047539, 2023). "Treatment with EJ inhibits STAT3, which reduces the expression and secretion of the MMP-2 and MMP-9 proteins and exerted an anti-tumor metastasis effect." (PMID 37049904, 2023).
tumor (continued). "In tumor cells, LRP1, as the endocytic receptor of MMP2 and MMP9, can make malignant cells in an adherent state by activating ERK and inhibiting the JNK signaling pathway, which is conducive to invasion 49,50,51." (PMID 36605486, 2023). "The publication focuses on the problem of changes in the gene expression of MMP2, MMP9 and tissue inhibitor of metalloproteinases (TIMP1) in the blood of NSCLC patients during therapy (one year after surgical resection of the tumor)." (PMID 37509417, 2023). "Multiple studies have suggested that, alongside its inhibitory effects on MMP-2/9, TIMP-2 can foster tumor cell proliferation, facilitate invasiveness/metastasis, and impede tumor cell apoptosis." (PMID 38276258, 2023). "Using a single whole-brain X-irradiation performed 20 h before NP injection, the expression of the CTX targets, MMP-2 and ClC-3 was enhanced as evidenced by the BBB permeabilization and increased internalization of Ag-PNP-CTX at the tumor site in vivo." (PMID 37444498, 2023). "In HCC, abnormal activation of Nrf2 promotes the expression of MMP2 and MMP9, which are matrix metalloproteinases that can degrade the basement membrane and promote tumor migration and invasion." (PMID 37174639, 2023). "Western blot experiments further showed that the expression levels of the tumor metastasis markers, matrix metallopeptidase 9 (MMP9) and MMP2, were decreased significantly in C918 cells after TAP1 silencing." (PMID 36774490, 2023). "In spite of that, Ginsenoside Rh2 was also proven to transform the macrophage phenotype from M1 to M2, thereby decreasing VEGF, MMP-2, and MMP-9 expression, eventually inhibit the spread and enlargement of tumours." (PMID 37742025, 2023). "Strong positive correlations were found between CD31 levels in primary tumor tissue and FABP4+MMP9+MMP2+TIMP1- (r = 0.82, p < 0.05) and FABP4+MMP9+MMP2-TIMP1- (r = 0.67, p < 0.05) populations of plasma sEVs." (PMID 37109070, 2023). "BC002811 regulated three differentially expressed genes (MMP2, MMP9, and PTEN) out of 84 key genes involved in human tumor metastasis." (PMID 36778127, 2023). "MMP2 and MMP9 participate both in the formation of new blood vessels and lymphangiogenesis, enabling adequate blood supply to the tumor, as well as the penetration of cancer cells into blood and lymphatic vessels." (PMID 37509417, 2023). "qRT-PCR analysis with PANC-1 and BxPC-3 cells confirmed that circEIF3I KD inhibited the mRNA expression of MMP2, MMP9 and MMP14, which are closely related to tumour invasion and metastasis." (PMID 37689715, 2023). "In RCC patients, the increased expression of MMP-2/-9 and TIMP-1/-2 is related to high tumor grade and shortened survival." (PMID 36614308, 2023). "Integrin αvβ3 is necessary for tumor cell adhesion to the extracellular matrix (ECM) by targeting RGD (Arg-Gly-Asp) in fibronectin and regulates MMP (especially MMP-2 and MMP-9) expression through the PI3K signaling pathway to hydrolyze collagen in the ECM." (PMID 37862114, 2023). "Specifically, our protein expression data showed both a trend of increased MMP2 levels and a significant increase in MMP9 levels in lungs from mice growing orthotopic MDA-MB-231-tdTomato tumor xenografts compared to lungs from normal mice as controls." (PMID 37903851, 2023). "The matrix metalloproteinases (MMPs), especially MMP-2 and MMP-9, can degrade extracellular matrix components, which are closely related to the tumor migration and metastasis." (PMID 37221457, 2023). "The analysis showed that the content of HSP60+, MMP9+MMP2+TIMP-, MMP9+2-TIMP-, and MMP9+2-TIMP+ populations of sEVs differed in patients with complete and partial tumor response." (PMID 37109070, 2023). "The results of the analysis showed the presence of correlations between the expression of MMP2, MMP9 and, interestingly, TIMP1 in tumor tissue or blood." (PMID 37509417, 2023).
tumor (continued). "MMP-2 is also able to produce elastin-derived matrikines composed of specific peptides (VGVAPG or AGVPGLGVG) and they were revealed to promote tumor progression." (PMID 37681919, 2023). "MMP-2 and MMP-9 are often considered targets for antitumor therapy due to their crucial roles in degrading the extracellular matrix and promoting tumor invasion and metastasis." (PMID 38003553, 2023). "Antibody activation through demasking is typically mediated by proteases, such as serine proteases (e.g. matriptase), matrix metalloproteinases (e.g. MMP-2/MMP-9) and cysteine proteases (e.g. cathepsin S) frequently overexpressed in tumor tissues." (PMID 37841262, 2023). "In a variety of malignant tumors, MMP-2 and MMP-9 overexpression generally leads to increased tumor angiogenesis, invasion, and metastasis." (PMID 36980704, 2023). "It inhibits the generation of M2 markers, IL-10, MMP-2/9, VEGF, and MCP-1, which is major determinants of macrophage recruitment at tumor sites." (PMID 37560476, 2023). "MMP2 and MMP9 are two matrix metalloproteinases that play a critical role in tumor cell invasion and metastasis." (PMID 37270527, 2023). "CHI3L1 also induces the expression of pro-tumorigenic molecules, including CXCL2, MMP-2, and MMP-9, which contribute to tumor growth and proliferation." (PMID 37480002, 2023). "Following tumor penetration across the brain endothelial barrier, the tumor cells invaded the ECM, as indicated by several epithelial–mesenchymal transition markers, including endopeptidases, MMP-2 and MMP-9, and an invasion marker, TWIST." (PMID 38001146, 2023). "This protein not only degrades extracellular matrix protein but also acts as an activator of other MMP zymogen including MMP2 and MMP9, playing a key role in tumor invasion." (PMID 37229458, 2023). "The results of the study revealed that PTC tissues exhibited significantly higher expression levels of MMP-2, MMP-9, and MMP-14 compared to adjacent non-tumor tissues." (PMID 38089632, 2023). "Luteolin further determines the suppression of matrix metalloproteinase-2 (MMP-2) and MMP-9, thus inhibiting angiogenesis an invasion, two key mechanisms of tumor progression and metastasis." (PMID 38203299, 2023). "Table 3shows the tumor volume and plasma levels of TF, PAI-1, IL-6, and MMP-2 on day 21 in UTR mice and water-treated or EDX-treated Colon26-inoculated mice." (PMID 36751299, 2023). "As demonstrated by our findings, ECM-modulating genes, such as MMP2 and MMP14, were clearly upregulated in the CAFs, and CAFs were found to secrete PDGFRA and CXCL12, which promote tumor progression, further validate the accuracy of CAF classification." (PMID 37565899, 2023). "The result of the statistical analysis did not confirm any correlation between the expression of the studied genes (MMP2, MMP9, TIMP1) in blood and tumor tissue." (PMID 37509417, 2023). "The protein expression levels of MMP-2 and MMP-9, which are proteins that indicate tumor invasiveness, were found to decrease in ezetimibe-treated groups." (PMID 36843944, 2023). "Reversion-inducing-cysteine-rich protein with Kazal motifs (RECK) also functions as a tumor invasion suppressive protein by inhibiting the proteolytic activity of MT1-MMP and MMP-2 in addition to its influence on MMP-9 expression." (PMID 37681919, 2023). "Next, we evaluated the effect of HNGF6A on the secretion of active metalloproteases (MMP) MMP-2 and MMP-9, which are essential for tumor cell invasion, by means of zymography in media from GBM U251-MG cells treated with HNGF6A." (PMID 37627089, 2023). "The temperature-sensitive NIL-IM-Lip is firstly delivered to tumours, then directed to the LNs following pH-sensitive shedding of NGR motif and MMP2-responsive release of IL-15." (PMID 37076492, 2023). "The IHC staining revealed a significant decrease in the expression of MMP-2, MMP-9, N-cadherin, and Vimentin in DMC-HA-treated tumor tissues." (PMID 38154100, 2023).